BRAF (B-Raf proto-oncogene, serine/threonine kinase)
Diseases named in the same sentence as BRAF in open-access papers (continued):
Sharing a sentence is not in itself a finding about the gene and the disease.
cancer (continued). "We also identified another 40 MAPK pathway genes (including MAPK1, BRAF and MAPK14) that are classifiable as “strongly selective” (see the “Methods” section) across various cancer cell lines." (PMID 33398072, 2021). "This is promising, indicating that cancer samples with higher TIS (i.e., tend to be immune-hot) are more sensitive to those drugs, especially those BRAF inhibitors." (PMID 33741950, 2021). "EGFR/BRAF, EFRF/KRAS, KRAS/ERBB2 demonstrated a mutually exclusive relationship, consistent with the recent evidence from cancer genomic studies which demonstrated that driver genes are often mutated in a mutually exclusive manner." (PMID 35186718, 2021). "Fusion events were detected in BRAF and FGFR3 in SKCM and HNSC cancer types, respectively, with high expression as compared with wild types." (PMID 34429404, 2021). "Targeted therapies against the components of mitogen-activated protein kinase (MAPK) pathways, including RAS, RAF, MEK, and ERK, have demonstrated activity in BRAF mutant and, in limited cases, RAS mutant cancer." (PMID 34830283, 2021). "RTK-driven feedback reactivation of AKT or ERK signaling has been identified as a key driver of drug resistance in cancers treated with AKT and mTOR inhibitors or BRAF and MEK inhibitors." (PMID 34790119, 2021). "In contrast, BRAF and ATM are both well-established cancer driver genes, and these two kinase-containing genes were found mutated in 8 and 5% of cancers, respectively." (PMID 34645806, 2021). "In NSCLC, clear evidence of resistance to BRAF and MEK inhibitors are yet to be reported.Because cancers are virtually usually multiclonal and genetically heterogeneous, combination therapy is widely recommended." (PMID 34692523, 2021). "SHP2 inhibition can be efficacious in targeting for BRAF RAS-GTP cancers, inactivation of neurofibromin 1 (NF1), and RAS cancers in which an oscillation of RAS is seen." (PMID 34845311, 2021). "BRAF, especially the mutant type BRAFV600E, has been found to enhance cancer radioresistance by promoting DNA repair by stimulating 53BP1 and RAD51." (PMID 33228740, 2020). "In contrast, cell proliferation gene (BRAF), ECM-degrading gene (MMP9), cell cycle regulating and WNT signalling pathway regulator (APC) were expressed higher in the cancers of early pathological stages." (PMID 33092235, 2020). "Our results also showed that the cancer cell-selective toxicity of AA was dependent on ROS, which is consistent with an increase of the mitochondrial-derived ROS in KRAS and BRAF mutant cells." (PMID 33071784, 2020). "Methylation profiling of BRAF mutant and APC mutant cancers confirmed this model, and showed that BRAF mutant cancers had a methylation profile reminiscent of the intestinal stem cell (p)." (PMID 32384699, 2020). "Previously, two molecular subtypes of PTC, namely BRAF V600E and RAS, were proposed based on transcriptome analysis of the cancer genome atlas (TCGA) database." (PMID 32240105, 2020). "Fusions with ADK, BRAF, and NTRK1 were reported repeatedly both in our cohort and in multiple cancer types." (PMID 32471990, 2020). "Differentiation of BRAF FOXE1+/+ and BRAF FOXE1+/− cancers was analyzed by IHC for two representative differentiated thyroid markers, the transcription factor PAX8, and the precursor of thyroid hormones thyroglobulin (TG)." (PMID 33375029, 2020). "In fact, in many cancer models, the removal of c-Myc, H-Ras, K-Ras, EGFR, mutant BRAF, c-Kit, or Met leads to growth arrest, differentiation, and apoptosis." (PMID 32528950, 2020). "This category also includes many known biomarkers for cancer diagnosis or targeted treatment, such as APC Q1291* (for COAD), EGFR L858R (for LUAD), BRAF V600E (for THCA and SKCM), DNMT3A R882H and NPM1 W288Cfs*12 (for LAML)." (PMID 31925297, 2020).
cancer (continued). "The probability of BRAFV600E-positive [BRAF(+)] metastatic lesions when the primary cancer lesion was BRAF(+) and BRAFV600E-negative [BRAF(−)] metastatic lesions when the primary cancer lesion was BRAF(−) was calculated." (PMID 33150263, 2020). "To identify the genes that confer resistance to BRAF inhibition, we designed a new CRISPR sgRNA library targeting 6000 cancer-related genes (6K-cancer library) based on COSMIC and OncoPanel." (PMID 32413516, 2020). "We found that across all three groups 81% of patients with a known molecular target (EGFR, ALK, ROS or BRAF) received a TKI, 91% if considering only those patients who received any cancer specific treatment." (PMID 32470017, 2020). "Since BRAF-mutant cancer cells are highly dependent on MEK/ERK signaling, the combination of a BRAF inhibitor and a MEK inhibitor (double therapy) has shown a slight increased activity in comparison with either agent alone." (PMID 32545884, 2020). "For example BRAF/MEK inhibitors promote the release of cancer cell antigens, cancer antigen presentation, infiltration of T cells into tumors, recognition of cancer cells by T cells and killing of cancer cells." (PMID 31947592, 2020). "However, the intersection of immunology and cancer biology creates challenges whereby a single genomic driver or biomarker (for example BRAF, KIT, or EGFR mutations in targeted therapies) do not adequately explain or predict response among patients being treated with anti-PD1 therapies." (PMID 32708981, 2020). "Yun's article stating that Vc selectively kills KRAS and BRAF mutant CRC makes us regain confidence in the study of Vc, a controversial cancer suppressor." (PMID 33293956, 2020). "First line, FDA-approved therapies targeting MAPK signalling, which include BRAF and MEK inhibitors, have variable success across cancers, and a significant number of patients quickly develop resistance." (PMID 32411231, 2020). "Strikingly, in both RAS- and BRAF-mutant cells, most resistance mechanisms lead to ERK-pathway reactivation, highlighting the strong ‘oncogene addiction’ of these cancers to ERK-signalling." (PMID 31182717, 2019). "YAP is involved in resistance to a variety of chemotherapeutic drugs in several cancer types, including molecular targeted drugs such as inhibitors of CDK4/6, EGFR and BRAF, as well as classical cytotoxic drugs such as 5-FU, cisplatin (CDDP) and doxorubicin." (PMID 31540262, 2019). "We examined a cohort of BRAF‐wild‐type cancers and BRAF‐mutant cancers, further stratified by microsatellite instability status, and found KLF5 to be significantly elevated in BRAF‐mutant cancers." (PMID 30478887, 2019). "Mebendazole has been recently reported to suppress multiple oncogenic targets in cancer cells, including hedgehog, VEGFR2, BRAF, BCR-ABL, and MYB35–38." (PMID 31727951, 2019). "The pathway Signaling by FGFR1 was enriched with cancer drivers and had a CT drug target with an interaction < 100 nM, BRAF (B-Raf Proto-Oncogene, Serine/Threonine Kinase)." (PMID 31214023, 2019). "These efforts have resulted in several cancer drugs that target activated driver oncogenes, such as HER2, BCR-ABL, EGFR, and BRAF." (PMID 31671773, 2019).
cancer (continued). "SMIs against BCL-2, IDHs, BRAF, PI3 kinase, mTOR, PARP, and CDKs have become the mainstay in the treatment of a variety of cancer types." (PMID 31807308, 2019). "BRAF has become an intriguing pharmacological candidate in recent studies, because of the failure to directly target mutant RAS in patients with cancer." (PMID 30743998, 2019). "In fact, constitutive ERK activation is responsible for NIS repression in a fraction of TC, and NIS repression extent correlates with the degree of MAPK activation, which is higher in BRAF-mutant than in RTK- and RAS-mutant cancers." (PMID 31181609, 2019). "In contrast, several agents, such as cabozantinib (VEGFR, MET, RET), ABT-888 (PARP), dabrafenib (BRAF), imatinib (Bcr/Abl), and sunitinib (PDGFR), demonstrated relatively minimal anti-cancer activities." (PMID 31771620, 2019). "MEK kinase, which is potently activated by BRAF in the RAS/RAF/MEK/ERK pathway, has also been explored as a target for new anti-cancer agents." (PMID 30975211, 2019). "Therefore, BRAF may either promote or inhibit cancer depending on the context." (PMID 31888644, 2019). "Furthermore, patients with late-stage BRAF mutant cancers were less likely to have a metastasectomy most likely due to the higher incidence of peritoneal involvement, and survival following metastasectomy was significantly shorter for patients with BRAF mutant compared to BRAF wild-type cancers." (PMID 30598662, 2018). "RHEB Y35N expressing cells undergo cancer transformation due to decreased interaction between RHEB and BRAF resulting in overactive RAF/MEK/ERK signaling." (PMID 29320991, 2018). "Additional biomarkers currently being studied for application in cancer treatment include the PIK3CA, HER2, BRAF, ROS, RET, NRAS, MET, and MEK1." (PMID 29721208, 2018). "Genome-wide single-nucleotide polymorphism (SNP) arrays also found a frequent and similar rate of copy number aberrations occurring in BRAF mutant/MSS and BRAF wild-type cancers." (PMID 30598662, 2018). "Longitudinal BRAF monitoring showed that, a reduction in AF at 4 and 12 weeks after commencing treatment was significantly associated with longer PFS and OS, indicating that an early drop in cfBRAFV600E levels could be predictive of survival when monitoring advanced stage cancers using cfDNA." (PMID 30220966, 2018). "A proportion of the BRAF mutant lesions remain as microsatellite stable (MSS), and in contrast to the MSI cancers, they have an aggressive phenotype and correlate with poor patient outcomes." (PMID 30598662, 2018). "Here, we found fusion genes involving BRAF, NTRK3, ALK, FGFR1, and ROS1, which result in activation of the MEK/ERK pathway in other cancers." (PMID 29654269, 2018). "CK20 was retained in BRAF mutant/MSS as typically seen in BRAF wild type, but lost in BRAF mutant/MSI cancers." (PMID 30598662, 2018). "A further study examining overall survival associated with post-lung metastasectomy found that it was significantly worse for BRAF mutant compared to KRAS mutant and wild-type cancers." (PMID 30598662, 2018). "BRAF V600E constitutively increases the activity of serine/threonine protein and activates MAPK signaling pathways in human cancers." (PMID 29713312, 2018). "Our results suggest that therapies targeting key oncogenes BRAF and AXL result in a regain of RIPK3 expression in cancers that have lost it." (PMID 30157175, 2018).
cancer (continued). "Overall, these observations strongly suggest that pathways downstream of BRAF and AXL are responsible for RIPK3 expression suppression and escape from necroptosis in cancer." (PMID 30157175, 2018). "Complexes of this group of proteins have been shown to function as a nexus of resistance to anti-BRAF and anti-MEK cancer therapies and were also found up-regulated in the samples of patients with poor response to MAPKi treatment." (PMID 29541007, 2018). "However incidence of non-V600 BRAF mutation is not negligible in certain cancer types." (PMID 29739364, 2018). "For example, oncogenic EGFR-KDD and BRAF-KDD have been reported in human cancers, along with their responses to the respective targeted therapies against EGFR and BRAF." (PMID 29455648, 2018). "These instances are listed in the Dataset EV2 and they included, among others, RBL2, KLF5, and ARAF as homologs of cancer drivers RB1, PBX1, and BRAF, respectively." (PMID 29572294, 2018). "This rise was due to alterations at a low percentage in genes with proven predictive value in the context of approved anti-cancer drugs (e.g., EGFR, BRAF, ERBB2, BRCA1, BRCA2, RET, ALK) in all cancer types." (PMID 29544535, 2018). "The mechanism of reactivation of telomerase in cancers has been recently reported to take place by recruitment of transcription factor such as GABPA or BRAF specifically to mutant TERT promoters, hence driving TERT transcription." (PMID 29907642, 2018). "We identify BRAF and NTRK1 as additional cancer genes operative in both malignancies, substantiating the view that these diagnoses represent variants on the same disease spectrum converging on aberrant RAS-RAF-MEK-ERK signaling." (PMID 29915264, 2018). "We also observed several mutations in the MAP kinase signaling pathway (14% of tumors), involving KRAS, NRAS, BRAF, and MAP2K1 oncogenes across multiple cancer types including hematologic, lung, ovarian, duodenal, biliary, and colorectal." (PMID 29100271, 2017). "The phase II MyPathway trial evaluated agents targeting the HER2, BRAF, Hedgehog, or EGFR pathways in patients with advanced cancer." (PMID 29285234, 2017). "The presence of different combinations of BRAF isoforms might contribute to explaining the highly heterogeneous degree of responses to BRAFi commonly observed among patients carrying different cancer types, and even among patients carrying the same cancer type." (PMID 28454577, 2017). "In contrast, targeted therapeutic agents, which block individual pathways that cancer cells are addicted to (such as EGFR, BRAF, MET or HER2 signaling), are specific for cancer cells and have potentially fewer side effects." (PMID 28420162, 2017). "While BRAF and EGFR inhibitors can produce dramatic responses temporarily, acquired resistance inevitably occurs in lung and other cancers." (PMID 28145866, 2017). "The model includes dendritic and cancer cells, CD 4+ and CD 8+ T cells, MDSC cells, interleukins IL-12, IL-2, IL-6, IL-10 and TGF- β, PD-1 and PD-L1, and the two drugs: BRAF/MEK inhibitor (with concentration γB) and PD-1 inhibitor (with concentration γA)." (PMID 28724377, 2017). "Our method revealed 3D clusters in all three RAS proteins (K/N/H-RAS), RAC1, BRAF, MAP2K1, and MAPK1 in a variety of cancer types." (PMID 28115009, 2017). "Here, we also validate potency of MEKi treatment against multiple, previously uncharacterized BRAF-fusions that have been discovered in PLGGs, some of which, like MKRN1-BRAF, co-occur in diverse adult cancers." (PMID 29156677, 2017). "The RAF serine/threonine kinases (ARAF, BRAF and CRAF) are arguably the most important effectors of mutant RAS-dependent cancer growth, as they have a key driver role in RAS-mediated oncogenesis." (PMID 29184501, 2017).
cancer (continued). "These include cancer hallmarks of various types: oncogenes (BCL2, BRAF), caspases (CASP6/7), transcription factors (E2F3), cell cycle genes (CDC42, CDK2, CDKN2A), cancer related kinases (JAK2/3, MAPK4/6/14) and DNA repair genes (BRCA1, PARP1 and RAD50)." (PMID 28059167, 2017). "Immunohistochemistry was used to detect the differential expression of KRAS, BRAF and MLH1 in cancer tissues." (PMID 27323816, 2016). "Next, we used FISH to determine the absolute copy number at loci harboring cancer-relevant genes: ALK, ROS1, MET, BRAF and RET." (PMID 27100738, 2016). "The high frequency of this particular mutation was further validated in the second series of formalin fixed cancers where it was found in 25/35 (71.4%) BRAF mutant/MSI, 1/12 (8.3%) BRAF mutant/MSS and 0/22 BRAF wild type cancers (p<0.0001)." (PMID 27661107, 2016). "BRAF mutant/MSI cancers had a low rate of deletion (4/30, 13.3%), which was expected since MSI cancers are known to be diploid." (PMID 27661107, 2016). "Because some client proteins (e.g., HER2, BRAF, and MET) play an important role in tumorigenesis, HSP90 is considered as a druggable target for cancer treatment." (PMID 27409672, 2016). "Some of the significantly mutated indel regions occur within genes with a well-established connection with cancer development, such as KIT, BRAF or PTEN." (PMID 27150584, 2016). "The most common type of RNF43 mutation was a frameshift at nucleotide 659 (G7 repeat tract) in exon 9 that occurred in 43/54 (79.6%) BRAF mutant/MSI, in 1/33 (3.0%) BRAF mutant/MSS and 0/79 BRAF wild type cancers." (PMID 27661107, 2016). "The most commonly mutated domain is the Tyrosine kinase domain observed in 20 different proteins, including such well-known cancer driver genes as ALK, EGFR or BRAF." (PMID 27150584, 2016). "Resistance through BRAF-inhibitor bypass and the development of RAS-driven secondary cancers in responses to BRAF inhibition have prompted the development of combination therapies with BRAF and MEK inhibitors." (PMID 27200346, 2016). "The status of MLH1, BRAF and KRAS expression, as well as inflammation related TNF-α, COX-2, MMP-9, β-catenin and NF-κB of cancer tissues were assessed to calculate their correlation with different microbial phylotypes." (PMID 27323816, 2016). "At the ZNRF3 locus, 22q12.1, there was a high frequency of deletion events in MSS cancers (BRAF mutant/MSS: 16/33, 48.5%; BRAF wild type: 10/18, 55.6%)." (PMID 27661107, 2016). "Cytoplasmic staining was least frequent in the BRAF mutant/MSI compared to BRAF mutant/MSS and BRAF wild type cancers (p=0.009)." (PMID 27661107, 2016). "MiR-143 and miR-145 target KRAS, BRAF and MEK2 in colorectal cancer and also in other types of cancer such as prostate tumors." (PMID 26287249, 2015). "For example, genes with Motif 1 in Molecular Mechanisms of Cancer pathway include MAPK1, BRAF, SMAD2, FZD5, FZD8, NOTCH1 and LRP1, whereas genes with Motif 2 and/or Motif3 in the same pathway include LRP5, LRP6, MDM2, CTNND1, SMAD3, SMAD4 and SMAD7." (PMID 26040697, 2015). "In conclusion, our study combined with previous studies showed that miR-19b controls at least two distinct oncogenic signaling (PI3K and BRAF/MAPK) and telomerase dependent pathways that are involved in cancer progression." (PMID 25643913, 2015). "However in the subgroup of patients with no nodal metastases (N0) there was no single event of cancer relapse, thus the analysis of the association with clinical parameters and BRAF status in multivariate setting was impossible if nodal metastases have been considered a variable in the model." (PMID 26177218, 2015). "To address the functional relevance of miRNAs in mutant KRAS cancers, we transfected exogenous KRASG12V into human embryonic kidney 293 and MRC5 cells with wild-type KRAS and BRAF genes, and we comprehensively profiled the dysregulated miRNAs." (PMID 25756961, 2015).